TAMM41 (TAM41 mitochondrial translocator assembly and maintenance homolog)
Description:
Catalyzes the conversion of phosphatidic acid (PA) to CDP-diacylglycerol (CDP-DAG), an essential intermediate in the synthesis of phosphatidylglycerol, cardiolipin and phosphatidylinositol.
Synonyms: TAM41; C3orf31; MGC16471; DKFZp434E0519; COXPD56; RAM41
Tractability: Antibody: UniProt places it where antibodies can reach, with medium confidence. PROTAC: its protein half-life has been measured.
Gene: Protein-coding gene on chromosome 3 (11,790,442 to 11,846,919, reverse strand). Ensembl gene ENSG00000144559.
Subcellular location: Mitochondrion inner membrane
Subcellular location (Human Protein Atlas): Cytosol
Gene Ontology:
Molecular function: protein binding; phosphatidate cytidylyltransferase activity
Biological process: cardiolipin biosynthetic process; CDP-diacylglycerol biosynthetic process
Cellular component: mitochondrion; mitochondrial inner membrane; mitochondrial matrix
Genetic constraint (gnomAD): Loss-of-function variants: 31 observed, 38.76 expected, observed/expected ratio (o/e) 0.8, 90% interval 0.6 to 1.08. The upper end of that interval is the gene's LOEUF score, 1.08, which puts it in group 4 of 6, group 1 being the genes least tolerant of losing a copy. Missense variants: 394 observed, 399.97 expected, observed/expected ratio (o/e) 0.99, 90% interval 0.91 to 1.07. Synonymous variants: 157 observed, 155.21 expected, observed/expected ratio (o/e) 1.01, 90% interval 0.89 to 1.15.
Gene-disease validity (ClinGen):
ClinGen rates the evidence that TAMM41 causes each of these diseases.
mitochondrial disease (autosomal recessive): Moderate.
Homologues: Orthologues: macaque TAMM41 (96% identical), chimpanzee TAMM41 (93% identical), dog TAMM41 (89% identical), guinea pig TAMM41 (87% identical), mouse Tamm41 (82% identical), pig TAMM41 (78% identical), rat Tamm41 (77% identical), zebrafish tamm41 (62% identical), Drosophila melanogaster CG33331 (39% identical), Caenorhabditis elegans Y71F9B.2 (36% identical).
Diseases named in the same sentence as TAMM41 in open-access papers:
TAMM41 is named in the same sentence as 14 diseases in open-access papers, as found by Europe PMC text mining. Sharing a sentence is not in itself a finding about the gene and the disease. The quoted sentences say what the papers report.
congenital heart disease (1 paper, 2019). A heart disease that is present at birth. "TAMM41, located within the congenital heart diseases (CHD) sensitive region of 3p25 deletion syndrome, is a mitochondrial membrane maintenance protein critical for yeast survival, but its function in higher vertebrates remains unknown." (PMID 30824836, 2019).
cardiovascular disease (1 paper, 2019). "To find out whether TAMM41 was involved in heart development, we examined its function using zebrafish models, which have proved an excellent model for studying human cardiovascular disease." (PMID 30824836, 2019).
kidney disease (1 paper, 2020). "Increased methylation of TAMM41 gene would act to repress gene transcription suggesting that loss of TAMM41 function may be linked with the development of kidney disease." (PMID 32117988, 2020).
tumour (1 paper, 2022). "Genes specifically lost in tumour samples with high NCS include KIAA1644, TAMM41, GRM7, TTC39B and FREM1." (PMID 35326573, 2022).
TAMM41 also shares sentences with these, for which no sentence is quoted: ataxia syndrome (1 paper); cardiomyopathy (1); gallbladder cancer (1); gastric cancer (1); melanoma (1); myopathy (1); neutropenia (1); pancreatic cancer (1); Progressive encephalopathy (1); sarcoma (1).